PCMTD1 (protein-L-isoaspartate (D-aspartate) O-methyltransferase domain containing 1)
Description:
Substrate recognition component of an ECS (Elongin BC-CUL5-SOCS-box protein) E3 ubiquitin ligase complex which mediates the ubiquitination and subsequent proteasomal degradation of target proteins. Specifically binds to the methyltransferase cofactor S-adenosylmethionine (AdoMet) via the N-terminal AdoMet binding motif, but does not display methyltransferase activity. May provide an alternate maintenance pathway for modified proteins by acting as a damage-specific E3 ubiquitin ligase adaptor protein.
Synonyms: FLJ10883
Tractability: Antibody: the Human Protein Atlas places it where antibodies can reach. PROTAC: ubiquitination databases record sites on it; its protein half-life has been measured.
Gene: Protein-coding gene on chromosome 8 (51,817,575 to 51,900,042, reverse strand). Ensembl gene ENSG00000168300.
Subcellular location: Cytoplasm; Membrane
Subcellular location (Human Protein Atlas): Plasma membrane; Nucleoplasm
Gene Ontology:
Molecular function: protein binding; S-adenosylmethionine-dependent methyltransferase activity; ubiquitin-like ligase-substrate adaptor activity
Biological process: protein ubiquitination
Cellular component: Cul5-RING ubiquitin ligase complex; cytoplasm; membrane
Genetic constraint (gnomAD): Loss-of-function variants: 8 observed, 32.57 expected, observed/expected ratio (o/e) 0.25, 90% interval 0.14 to 0.44. The upper end of that interval is the gene's LOEUF score, 0.44, which puts it in group 1 of 6, group 1 being the genes least tolerant of losing a copy. Missense variants: 207 observed, 378.8 expected, observed/expected ratio (o/e) 0.55, 90% interval 0.49 to 0.61. Synonymous variants: 100 observed, 126.27 expected, observed/expected ratio (o/e) 0.79, 90% interval 0.67 to 0.94.
Homologues: Orthologues: chimpanzee PCMTD1 (100% identical), guinea pig PCMTD1 (99% identical), macaque PCMTD1 (99% identical), pig PCMTD1 (99% identical), mouse Pcmtd1 (99% identical), tropical clawed frog PCMTD1 (90% identical), dog PCMTD1 (72% identical), rat Pcmtd1 (71% identical), rabbit PCMTD1 (63% identical), Caenorhabditis elegans R119.5 (27% identical). Paralogues in human: PCMTD2 (66% identical), PCMT1 (16% identical).
Diseases named in the same sentence as PCMTD1 in open-access papers:
PCMTD1 is named in the same sentence as 8 diseases in open-access papers, as found by Europe PMC text mining. Sharing a sentence is not in itself a finding about the gene and the disease. The quoted sentences say what the papers report.
asthma (1 paper, 2018). "We also identify previously unreported genes with concordant molecular changes in asthma: Shroom2, Pcmtd1, Zfp568 and 2310035C23Rik were significantly down/upregulated and hyper/hypo methylated." (PMID 30400597, 2018).
autism (1 paper, 2015). Persistent deficits in social interaction and communication and interaction as well as a markedly restricted repertoire of activity and interest as well as repetitive patterns of behavior. "These genes with identical genomic variants included KCNJ12, MLL3, OR9G1 and PCMTD1 with different mutations reported in other disease states and appeared to reflect artifacts in the present analysis of autism." (PMID 25574603, 2015).
diabetes (1 paper, 2020). "When we examined the super enhancers in NOD ES cells, we found that Pcmtd1, Fcgr3 and Igfbp2 are implicated in human diabetes from GWAS studies." (PMID 32796510, 2020). "We also performed NOD-specific super enhancer analysis using H3K27ac ChIP-Seq signals in NOD ES cells and found a subset of top super enhancers, Pcmtd1, CD16 and Igfbp2, which were previously implicated in diabetes genome-wide association studies (GWAS)." (PMID 32796510, 2020).
gastric carcinoma (1 paper, 2019). A carcinoma that arises from epithelial cells of the stomach. "Interestingly, the tongue SCC ITOC-02 cell line had truncating mutations in a few genes which are rarely associated with some cancers, PYROXD2, PCMTD1 reported to be mutated in hepatocellular cancer and PABCP1 reported to be upregulated in gastric carcinoma and targeting miR-34c38." (PMID 31164688, 2019).
glaucoma (1 paper, 2014). Increased pressure in the eyeball due to obstruction of the outflow of aqueous humor. "PGP-15 had a glaucoma-associated high-penetrance variant in the gene WDR36 (A449T), and PGP-88 had a rare variant (N286T) in the glaucoma-associated gene PCMTD1." (PMID 25188385, 2014).
cancer (3 papers, 2017 to 2021). A tumor composed of atypical neoplastic, often pleomorphic cells that invade other tissues. "Two of the called 3’ UTRs (DRD5 and PCMTD1) have previously been detected in cancer driver studies." (PMID 28362259, 2017).
PCMTD1 also shares sentences with these, for which no sentence is quoted: adenoma (1 paper); glioma (1).